PCK1 (phosphoenolpyruvate carboxykinase 1)
Diseases named in the same sentence as PCK1 in open-access papers (continued):
Sharing a sentence is not in itself a finding about the gene and the disease.
hepatocellular carcinoma (continued). "Forced PCK1 expression in glucose-starved hepatoma cells reportedly induces tricarboxylic acid cycle cataplerosis, leading to energy crisis, oxidative stress, and cell apoptosis." (PMID 30619751, 2018). "We also investigated the antitumor effect of auranofin combined with sorafenib in PCK1 knockout hepatoma cells in vitro." (PMID 30619751, 2018). "In hepatocellular carcinoma, high expression of phosphoenolpyruvate carboxykinase 1 (PCK1) accelerates the transition of the cell cycle from the G1 phase to the S phase under low glucose conditions by activating the CDK/Rb/E2F pathway, promoting the growth and division of liver cancer cells." (PMID 40525649, 2025). "Indeed, H4IIE hepatoma cells treated with buthionine sulfoximine, an inhibitor of glutathione synthesis also exhibit increased expression of Pck1." (PMID 39734207, 2024). "Xu and colleagues demonstrated that disrupting the interaction between INSIGs and SCAP (due to activation of the AKT/PCK1 axis in hepatocellular carcinoma cells) leads to activation of SREBPs and, consequently, lipogenesis that in turn increases cell proliferation." (PMID 38065937, 2023). "Moreover, metabolomic data showed that the serine synthesis pathway (SSP) is markedly upregulated in PCK1-overexpressing (PCK1-OE) hepatoma cells." (PMID 37166978, 2023). "PCK1 is downstream of the mTOR pathway; mTOR inhibition up-regulates PCK1 and shuttles glycolytic flux to the gluconeogenesis pathway, thereby inhibiting cellular proliferation in hepatocellular carcinoma and ccRCC." (PMID 37062825, 2023). "While the over-expression of PCK1 was declared in colon cancer, lung cancer, melanoma, and lymphoma, metastatic breast cancer cells, and skin cancer, the down-regulation of this gene is present in kidney cancer and hepatocellular carcinoma (HCC)." (PMID 35333898, 2022). "Recent studies have demonstrated a tumor suppressor role for PCK1 in hepatocellular carcinoma." (PMID 35159548, 2022). "Importantly, we found that PCK1 inhibits motility of hepatoma cell via downregulating cellular O-GlcNAcylation levels by detecting the cellular motility in response to OGT or OGA inhibition." (PMID 34650217, 2021). "Loss of phosphoenolpyruvate carboxykinase 1 (PCK1), the major rate-limiting enzyme of hepatic gluconeogenesis, increases hexosamine biosynthetic pathway (HBP)-mediated protein O-GlcNAcylation in hepatoma cell and promotes cell growth and proliferation." (PMID 34650217, 2021). "However, in liver cancer and hepatocellular carcinoma, PCK1 or PCK2 have been found to be downregulated and to inhibit cancer cell proliferation or tumor growth in vivo." (PMID 33540663, 2021). "Furthermore, V. baillonii exert insulin-mimicking effects by inducing phosphorylation of Akt and inhibit Pck1 mRNA levels in hepatoma cells." (PMID 34899339, 2021). "Considering that nutrients such as glucose in the culture medium are gradually consumed during long-term culture, we compared AMPK and pAMPK expression levels in PCK1-OE and PCK1-KO hepatoma cells cultured under low-glucose (1 mM) or normal-glucose (25 mM) conditions for 12 h." (PMID 30717766, 2019). "Together, these results suggested that PCK1 could inhibit hepatoma cell growth in vivo by decreasing ROS level and TXNRD1 expression." (PMID 30619751, 2018). "Finally, we found that auranofin, a TXNRD1 inhibitor, enhanced the sensitivity of PCK1-knockout hepatoma cells to sorafenib-induced apoptosis." (PMID 30619751, 2018). "Furthermore, overexpression of PCK1 suppressed reactive oxygen species (ROS) production and nuclear translocation of Nrf2 in hepatoma cells." (PMID 30619751, 2018). "Previous studies have found that PCK1 is downregulated in hepatocellular carcinoma (HCC), and KO of PCK1 enhances the proliferation and metastasis of HCC in vitro and in vivo." (PMID 37166978, 2023).
hepatocellular carcinoma (continued). "The hypothesis for these experiments was based on combinations of previous work using bovine hepatocytes, postruminal infusion of propionate, and research using reporter genes in hepatoma cells that point to the regulation of PC and PCK1 by propionate, palmitic, and linolenic acids." (PMID 38003190, 2023). "PCK1 is a gluconeogenic enzyme involved in gluconeogenesis and lipogenesis processes in hepatocellular carcinoma (HCC)." (PMID 36193307, 2022). "Finally, we examined the correlation between NFYA and PCK1 in human hepatocellular carcinomas." (PMID 36092708, 2022). "Interestingly, the G309R mutant that causes enzyme deficiency of PCK1 was unable to decrease the invasion and migration of SK-Hep1 cells, suggesting that the metabolic activity of PCK1 is required for suppressing the motility and invasiveness of hepatoma cells." (PMID 34650217, 2021). "Furthermore, transcriptome and cell cycle analysis revealed that PCK1 may suppress G1/S transition and cell proliferation in hepatoma cells via inhibiting the CDK/Rb/E2F signaling pathway." (PMID 30717766, 2019). "Thus, we examined NADPH/NADP+ ratio and ROS levels in hepatoma cells upon PCK1 expression." (PMID 30619751, 2018). "In hepatocellular carcinoma (HCC) cells, the inhibition of PCK1 reduced the phosphorylation of INSIG (insulin-induced gene) 1/2, leading to a suppression of cell proliferation and a decrease in tumorigenesis." (PMID 38670942, 2024). "To validate the effects of SHP-1 on PCK1 transcription in another liver cell line, we used Ptpn6 shRNA to knockdown Ptpn6 by about 50% in FAO rat hepatoma cells as compared to the control shRNA." (PMID 37595871, 2023). "Taken together, these observations indicate that PCK1 catalyzes TCA intermediates into SSP, maintaining a relatively high level of SAM and H3K9me3 modification in hepatoma cells." (PMID 37166978, 2023). "Of these 8 kinases, GALK1, PCK1 and PANK1 were highly expressed in normal liver tissues and down-regulated in hepatocellular carcinoma (HCC)." (PMID 35280671, 2022). "Phosphoenolpyruvate carboxykinase 1 (PCK1), a rate-limiting enzyme in gluconeogenesis, is phosphorylated by AKT in hepatocellular carcinoma (HCC) patients, and phosphorylated PCK1 translocates to the ER and acts as protein kinase to phosphorylates Insig-1 and Insig-2 in the ER." (PMID 35386193, 2022). "Here, we demonstrated that PCK1-induced AMPK activation increases p27Kip1 expression and suppresses hepatoma cell proliferation." (PMID 30717766, 2019). "Mechanistically, PCK1 decreases cellular ATP levels and activates the AMPK/p27Kip1 axis in glucose-deprived hepatoma cells." (PMID 30717766, 2019). "Phosphoenolpyruvate carboxykinase 1 (PCK1), a key enzyme in the gluconeogenesis pathway, is downregulated in hepatocellular carcinoma (HCC) and predicts poor prognosis." (PMID 30717766, 2019). "Moreover, together with the loss of growth arrest, the previous enhancement of maturation in the hepatoma line was significantly reduced as shown by decreased expression of maturation markers CYP3A4, ALB, AHR, GLUL, and PCK1." (PMID 38037844, 2024). "We found that wild-type (WT) PCK1, but not the G309R mutant, significantly suppressed lung colonization of hepatoma cells in nude mice, as determined by H&E staining of lung tissues and metastatic nodules." (PMID 34650217, 2021). "Our previous study has shown that PCK1 depletion increases global O-GlcNAcylation levels through oxaloacetate accumulation, de novo UTP synthesis and AMPK-GFAT1 axis inactivation promoting uridine diphosphate-N-acetylglucosamine (UDP-GlcNAc) biosynthesis in hepatoma cells." (PMID 34650217, 2021). "However, previous findings identified a specific role for the mammalian N-end rule enzyme UBR5 in degrading the gluconeogenic enzyme PCK1 under high-glucose conditions and a MAGE-TRIM28 E3 ligase complex targeting FBP1 for proteolytic degradation in a hepatocellular cancer background." (PMID 29911972, 2018).
hepatocellular carcinoma (continued). "The distinct expression profile of PCK1 in HCC tissues compared to other solid tumors can be explained by the fact that in the liver, which accounts for approximately 90% of gluconeogenesis, the upregulation of gluconeogenesis by PCK1 results in the suppression of hepatoma proliferation." (PMID 30619751, 2018). "Recent studies have reported upregulation and/or increased phosphorylation of PCK1 or PCK2 in different human malignancies, including colon cancer, non-small cell lung cancer (NSCLC), melanoma, and lymphoma, as well as metastatic breast cancer and hepatocellular carcinoma (HCC)." (PMID 34620839, 2021).
type 2 diabetes (29 papers, 2010 to 2025). "Both rs707555 and rs2071023 in PCK1 were significantly associated with type 2 diabetes in the minority population of Guangxi." (PMID 30805021, 2019). "Phosphoenolpyruvate carboxykinase 1 (PEPCK1) is the critical enzyme for gluconeogenesis and is linked with type II diabetes." (PMID 28127057, 2017). "Common variation at the PCK1 locus has also been associated with type 2 diabetes in a number of independent studies." (PMID 20574532, 2010). "Other variants in the PCK1 locus have shown modest evidence of association with Type II Diabetes Mellitus (T2DM)." (PMID 21152065, 2010). "Our findings suggest PCK1 plays a key role in the beneficial effects of oil tea, and PCK1 may be a potential genetic marker for the treatment of type 2 diabetes." (PMID 30805021, 2019). "Our findings indicated oil tea improved glucose homeostasis via down-regulation of PCK1 and PCK1 may be a genetic marker for the treatment of type 2 diabetes." (PMID 30805021, 2019). "In the present study, the PPAR pathway inhibited the expression of PCK1, suggesting that G. elegans could be used to inhibit the excessive production of glycogen via PCK1-mediated regulation of sugar dysplasia, thus improving metabolic diseases such as type II diabetes." (PMID 33919302, 2021).
Hypoglycemia (22 papers, 2005 to 2025). A decreased concentration of glucose in the blood. "For example, PCK1 deficiency, although rare, manifests as hypoglycemia, lactic acidosis, liver failure, and excessive excretion of tricarboxylic acid cycle metabolites in the urine." (PMID 39928707, 2025). "In the year 2014, a PCK1 variant was detected in two siblings who exhibited symptoms of lactic acidosis and hypoglycemia episodes." (PMID 37924129, 2023). "Compared with the administration of control virus expressing green fluorescent protein (AdGFP), AdTAZ administration caused relative hypoglycemia during fasting, which was accompanied by lower mRNA expression and protein levels of hepatic PCK1 and G6PC." (PMID 34622775, 2021). "Mutation of Pck1 gene causes Smith-Magenis Syndrome, where the patients have episodes of hypoglycemia and lactic acidosis." (PMID 28837672, 2017). "In mice carrying a targeted disruption of the CREB gene or expressing a dominant negative CREB protein in the liver, the induction of pgc-1α, g6pc, and pck1 by glucagon was blocked, and this led to severe hypoglycemia." (PMID 37048171, 2023). "Consistent with the observed relative fasting hypoglycemia with 5 mg/kg methomyl, mRNA expression of phosphoenolpyruvate carboxykinase (Pck1), the rate limiting step in hepatic gluconeogenesis, was significantly increased 1.7-fold (p = 0.0006)." (PMID 37623845, 2023). "They observed increased Fgf21 and lower Pck1 transcript levels, which counteracts hypoglycemia and energy imbalance." (PMID 34129049, 2021). "Reduced expression of key gluconeogenic genes including Pck1, G6Pc, and Pfkfb3 in L-GRKO mice is linked to fasting hypoglycemia, and around half of newborn albumin-alpha-fetoprotein-driven L-GRKO mice die within 48 h after birth, possibly due to hypoglycemia." (PMID 33133019, 2020). "Studies in Pck1-knockout mice confirmed the importance of Pck1 in hepatic gluconeogenesis and glucose homeostasis, as Pck1-/- mice display severe hypoglycemia." (PMID 25807515, 2015). "Previous studies have shown that knockout of Pck1 in mice leads to hypoglycemia and death, supporting the necessity of PEPCK for life in mammals, and making it unlikely that this gene in OWFBs underwent relaxed evolution." (PMID 25807515, 2015). "PCK1, PCK2, and FBP1, when deficient, have all been associated with hypoglycemia, and may have been upregulated as a compensatory mechanism to potentially provide needed intermediates within the glycolytic pathway." (PMID 38731997, 2024). "Indeed, PCK1-knockout mice die early after birth with profound hypoglycemia, which was partially rescued by the overexpression of PCK1 in the liver." (PMID 37904164, 2023). "Therefore, gluconeogenesis under the control of PCK1 in the liver is crucial to avoid hypoglycemia." (PMID 37904164, 2023). "Thus, reduced Pck1 expression in the heart might result in impaired gluconeogenesis, limiting the availability of glucose and potentially leading to a deficit in energy supply, especially under hypoglycemia conditions." (PMID 40301189, 2025). "The hepatic expression of the gluconeogenic genes Pck1 and G6pc expression was elevated in overnight fasted POMC-TC mice, probably as a compensatory mechanism to prevent hypoglycemia." (PMID 30230471, 2018).
Hyperglycemia (20 papers, 2007 to 2025). An increased concentration of glucose in the blood. "Ppargc1αis a key regulator of hepatic gluconeogenesis that contributes to circulating hyperglycemia, and liver-specific Ppargc1α-deficient mice have reduced Pck1 and G6pc expression and mild hypoglycaemia." (PMID 25405530, 2014). "Zebrafish also initiate gluconeogenesis during fasting similar to mammals and inhibition of the phosphoenolpyruvate carboxykinase gene (pck1) results in sustained hyperglycemia in zebrafish embryos." (PMID 35928228, 2022). "Increased E2F1 mRNA expression has been observed in diabetic patients liver biopsy samples which correlates with the levels of PCK1, which is concerned to hyperglycaemia development in mice and possibly also in humans." (PMID 32884568, 2020). "It has been reported that PCK1 is up-regulated in diabetic rodent models, and overexpression in the transgenic mice resulted in insulin resistance and hyperglycemia." (PMID 30805021, 2019). "Indeed, studies of the effect of Rosmarinic acid, insulin, retinoic acid and phenobarbital showed decreased expression of PCK1 and improvement of hyperglycemia in diabetic rats." (PMID 30805021, 2019). "CB0313.1 modulates gut microbiota composition to selectively enrich butyrate-producing bacteria, promote GLP-1 and insulin secretion, activate the GLP-1/insulin/pIRS1-pAKT-PPARγ-G6Pase/Pck1 pathway, and reduce hepatic glucose output, which ultimately mitigates hyperglycemia in diabetic host mice." (PMID 28765642, 2017). "Excessive HGP is a major contributor to both fasting and postprandial hyperglycaemia and is suppressed by insulin by inhibiting the expression of gluconeogenic enzymes, namely phosphoenolpyruvate carboxykinase 1 (Pck1), fructose-1,6-bisphosphatase (Fbp1) and glucose-6-phosphatase." (PMID 20977585, 2010). "It has been reported that liver-specific deletion of Sirt1 upregulates the expression of G6Pase and PCK1 by impairing the mTorc2/AKT/FOXO1 pathway and thus increases hepatic glucose production and chronic hyperglycaemia." (PMID 35132380, 2022). "Unexpectedly, qPCR showed reduced expression of G6PC, PCK1, FBP1 with the down‐regulation of SMC5, suggesting that hepatic gluconeogenesis is not the cause of hyperglycaemia." (PMID 36627765, 2023).
melanoma (19 papers, 2017 to 2025). A malignant, usually aggressive tumor composed of atypical, neoplastic melanocytes. "In colorectal cancer and melanoma, increased PCK1 expression is associated with upregulated anabolic metabolism and cell proliferation, indicating that PCK1 functions as an oncogene in these cancers." (PMID 30717766, 2019). "Compared with A2058 primary melanoma cells, the inhibition ability of the combination group was even more prominent, which suggested that the combination of BRAFi and PCK1 could achieve an excellent inhibition effect in resistant cells with PCK1 mutation." (PMID 36700470, 2022). "3-MPA, a PCK1 inhibitor, has been shown to significantly inhibit tumor growth and metastasis in mice with melanoma, CRC, or breast cancer." (PMID 39578429, 2024). "High PCK1 protein expression was detected in vilofinib-resistant melanoma cells, and further studies confirmed that PCK1 overexpression promoted cell proliferation and invasion, and reduced verofinib-induced oxidative damage." (PMID 39578429, 2024). "In human melanoma and colon carcinoma, expression of PCK1 is markedly up-regulated to promote tumor growth." (PMID 37013645, 2023). "In contrast to the tumor-promoting effects of PCK1 in melanoma, PCK2 downregulation has been indicated as a metabolic characteristic of TRCs from melanoma." (PMID 37250903, 2023). "The overexpression of phosphoenolpyruvate carboxykinase 1 (PCK1)-overexpressing T cells restricted tumor growth and prolonged the survival of melanoma-bearing mice." (PMID 36614197, 2023). "These lines of evidence illustrated that the activation of PCK1 potentiated melanoma proliferation, migration, and tumor stemness, all the phenotypes associated with drug resistance." (PMID 36700470, 2022). "We found that the Akt/PI3K/mTOR signaling pathway was activated in resistant melanoma cells, and then PCK1 was upregulated in also promoted cell proliferation, migration, and tumor stemness." (PMID 36700470, 2022). "In this study, we investigated the potential role of PCK1 in modulating the resistant phenotype of malignant melanoma." (PMID 36700470, 2022). "Ultimately, the biological processes mediated by PCK1 under the agonism of AKT are critical steps for drug resistance in melanoma." (PMID 36700470, 2022). "Although there are many downstream effectors of PI3K and Akt that can change the function of melanoma cells, PCK1 synthesis and activation are important processes mediated after AKT phosphorylation." (PMID 36700470, 2022). "Compared with the A2058R+vemurafenib group, the A2058R+3-MPA+vemurafenib group showed a significant increase of ROS but a decrease in the number of tumor cells, which demonstrated that the inhibition of PCK1 sensitized melanoma to vemurafenib." (PMID 36700470, 2022). "In this study, we aimed to investigate the potential role of PCK1 in regulating acquired drug resistance in melanoma." (PMID 36700470, 2022). "3-MPA blocked PCK1, thereby enabling ROS accumulation and suppressing chemoresistance in melanoma cells." (PMID 36700470, 2022). "In conclusion, this study disclosed that drug-resistant cells appeared to regulate their own proliferation, oxidative stress and tumor dryness by activating Akt/PCK1/ROS pathway, and shed new insights into acquiring drug resistance in melanoma." (PMID 36700470, 2022). "PCK1-overexpressing T cells restricted tumor growth and increased survival of melanoma-bearing mice." (PMID 32762776, 2020). "In this work, the authors demonstrated that, in tissue culture, melanoma ‘tumor re-initiating cells’ consumed more glucose and produced more lactate and glycerate-3-phosphate; PCK1 silencing elicited the opposite phenotype in culture." (PMID 31841108, 2019). "PCK1, while traditionally associated with gluconeogenesis, exhibits noncanonical functions in melanoma." (PMID 40565936, 2025).